CRP (C-reactive protein)
Diseases named in the same sentence as CRP in open-access papers (continued):
Sharing a sentence is not in itself a finding about the gene and the disease.
tumor (continued). "We hypothesized that markers of liver functional reserve and systemic inflammation, such as albumin levels and CRP/albumin ratio, would outperform classical tumor markers for early mortality prediction in this specific patient population." (PMID 41590616, 2025). "Our study is the first to describe CRP expression in the tumor tissue of PDAC patients." (PMID 37415393, 2025). "Comparison between survival groups in patients with neoplasms shows that survivors had significantly lower fibrinogen/CRP at T2 versus T0 (p = 0.046/p < 0.001) while differences from T0/T1 (p = 1.000/p = 0.065) or T1/T2 (p = 0.167/p = 0.065) were not significant." (PMID 41153844, 2025). "CRAFITY adds a tumor burden component (AFP) to inflammation (CRP), improving on single markers." (PMID 40568585, 2025). "Furthermore, serum hepcidin showed a strong positive correlation with CA15‐3 (r = 0.62, p < 0.001), CRP (r = 0.58, p < 0.001), and tumor stage (η2 = 0.47, p < 0.001), indicating its potential as a prognostic marker." (PMID 40791284, 2025). "The study demonstrated that both versions of the API and CRP were significantly higher in animals with shorter survival times (<30 and <90 days), supporting the hypothesis that the severity of tumor-induced inflammation has prognostic relevance." (PMID 40559770, 2025). "Firstly, the tumor microenvironment is known to induce a chronic inflammatory state, characterized by increased production of cytokines such as interleukin‐6 (IL‐6) and other acute‐phase inflammatory proteins such as CRP." (PMID 40791284, 2025). "In addition to assessing clinical symptoms at admission, blood tests were performed to measure serum Alb (g/dL), TTR (mg/dL), CRP (mg/dL), and tumor markers." (PMID 41181583, 2025). "Notably, clinical interpretation of CRP must account for tumor histotype and microenvironmental context." (PMID 40563367, 2025). "Importantly, the concentrations of C9, CRP, and LRG1 are significantly associated with tumor size, reinforcing their potential role in GBM prognosis and clinical stratification." (PMID 40628732, 2025). "CRP has been found to be a prognostic biomarker in several tumor entities and may reflect a pro-inflammatory tumor microenvironment." (PMID 40455253, 2025). "Inflammatory and immune components also play a key role: IL-6 mediates chronic inflammation and may promote tumor progression and treatment resistance, while CRP levels indicate systemic inflammatory responses." (PMID 41244922, 2025). "applied a novel CRP kinetics approach to nivolumab immunotherapy in metastatic renal cell carcinoma (mRCC), finding great tumour shrinkage and outcomes in ‘flare-responders’ whose CRP levels initially increased but then decreased within three months to levels below baseline." (PMID 41306979, 2025). "The reason may be that NC and CRP are affected by immune stress elements such as tumours, chemotherapy, etc., and fail to reflect the occurrence of bacterial infections specifically." (PMID 41281267, 2025). "Thus, further research into lymphodepleting regimens that add macrophage depletion is warranted, especially in groups at high risk of CRS such as patients with high tumor burden, high LDH, or high levels of CRP at the time of CAR-T therapy." (PMID 39812904, 2025). "In addition, previous studies have shown that CRP has been identified as a potential prognostic indicator in CRC, reflecting systemic inflammation associated with tumor progression." (PMID 40642165, 2025). "Elevated levels of CRP may reflect the inflammatory state of the disease and tumor burden, both of which can contribute to thrombus formation." (PMID 39960959, 2025). "Furthermore, it was reported that cytotoxic treatments in these patients slightly increase the CRP levels as a result of tumor destruction." (PMID 40125102, 2025). "Whether this stress-sensing mechanism extends to glycolysis-driven tumor cell phenotypes remains unresolved, but highlights CRP as a potential metabolic sentinel." (PMID 41614767, 2025).
tumor (continued). "We demonstrated that the CT-measured maximal sternal lymph node diameter has potential utility in evaluating systemic inflammation, based on its association with the measured plasma CRP concentration (also augmented with results for the WBC count), in small dogs free of neoplastic disease." (PMID 40284858, 2025). "Notably, CRP-based markers were found to be useful for predicting therapeutic response and long-term outcomes of patients with this tumor entity." (PMID 40615597, 2025). "The lack of association in our study could be due to the small sample size, limited variability in CRP levels, or the unique tumor biology of g‐NENs." (PMID 41466721, 2025). "The combination of these metabolic changes and elevated CRP jointly promotes tumor development." (PMID 39980561, 2025). "In fact, none of the interactions between time and the other factors (age, gender, mediastinoscopy, tumor position, side, histology, T stage, or N stage) showed a statistically significant effect on the CRP trajectory (all p > 0.25 after appropriate corrections)." (PMID 41153812, 2025). "PCT is a handy tool in the neurosurgical cohort since after a standard major neurosurgical operation (e.g. tumor resection, aneurysm clipping) or aneurysmal subarachnoid hemorrhage, leukocyte and neutrophil count, as well as C-reactive Protein (CRP), are significantly elevated." (PMID 40257674, 2025). "Elevated CRP levels typically indicate systemic inflammation, often driven by tumor progression." (PMID 41244206, 2025). "Furthermore, CRP is an acute-phase protein influenced by IL-6 and TNF-α, linked to tumor aggressiveness and cachexia." (PMID 40786260, 2025). "CRP is a model inflammatory protein, and lactate dehydrogenase has been recently viewed as a pivotal modulator of immunogenicity and metabolic activity of various neoplasms." (PMID 40496607, 2025). "CRP was assessed post-surgery while IS was derived from CD3 + /CD8+ cell densities in tumor tissue." (PMID 41291131, 2025). "Studies have also demonstrated that CRP could directly promoted tumor cell proliferation, invasion and migration." (PMID 40264786, 2025). "This metabolic shift not only supports cytokine release but also sustains fatty acid synthesis and trained immunity, suggesting that chronic CRP exposure may enforce a glycolysis-dependent inflammatory state within the tumor milieu." (PMID 41614767, 2025). "We found weak to moderate but significant positive associations of tumor levels (hVAF) with CA19‐9 (R = 0.416, P = 0.040), thrombocytes (R = 0.432, P = 0.024), neutrophils (R = 0.545, P = 0.020), LDH (R = 0.587, P = 0.001), and CRP (R = 0.421, P = 0.026)." (PMID 39840713, 2025). "The tumor's presence can elicit an inflammatory response, promoting elevated levels of interleukin-6 (IL-6), C-reactive protein, immunoglobulins, and erythrocyte sedimentation rate, contributing to systemic symptoms such as fever, malaise, anorexia, and weight loss." (PMID 40842978, 2025). "The tumour cells expressed serum amyloid A and C-reactive protein." (PMID 41321651, 2025). "CRP, on the other hand, contributes to tumor metastasis and invasion by promoting angiogenesis." (PMID 39963109, 2025). "Although the extracted factors explain 36.4% of the total variance, the results suggest that additional inflammatory markers, such as C-reactive protein or interleukin-6, might refine predictive models for tumor aggressiveness." (PMID 41010971, 2025). "The role of systemic inflammation in promoting tumor progression and metastasis may explain why CRP was an independent predictor of both OS and DFS in this study." (PMID 40277783, 2025). "Although limited data exists, HIF1α has been shown to induce the expression of CRP and other pentraxins in tumor cells and neurons, while CRP has been shown to stabilize HIF1α expression in adipose-derived stem cells as well as induce angiogenic activity in endothelial cells." (PMID 41614767, 2025).
tumor (continued). "Markers of systemic inflammation and tumor burden, such as C-reactive protein (CRP) and lactate dehydrogenase (LDH), may also provide prognostic information." (PMID 41200168, 2025). "Patients with more advanced tumor stages also showed elevated levels of CRP in their serum, and these increased levels may indicate poor prognosis and tumor progression." (PMID 39851610, 2025). "The predominance of albumin and CRP/albumin ratio over conventional tumor markers underscores that, in this specific population, host factors may be more decisive than tumor burden itself in shaping short-term prognosis." (PMID 41590616, 2025). "As such, CRP may alter cell–matrix adhesion and tissue architecture, as well as modulate cell–cell signaling that affects tumor progression." (PMID 41614767, 2025). "Further analysis of the relationship between CRP levels/activity and ceramide derivatives could provide insight on whether and how CRP could regulate the effects of ceramide/SM/S1P on tumor cells and their microenvironment." (PMID 41614767, 2025). "Serum C reactive protein and lactate dehydrogenase at 1 day following cryoablation, tumor’s nearness to the collecting system or sinus, and volume of ablated normal renal parenchyma were significantly correlated with decreased contributions of the affected kidney by > 10% after cryoablation." (PMID 38744807, 2024). "Low levels of IL6 and CRP may indicate a less inflammatory tumor microenvironment, which can enhance the effectiveness of treatment with ICIs." (PMID 38952546, 2024). "Recent evidence indicates that CRP is closely related to tumor immunosuppression." (PMID 38365678, 2024). "Additionally, the TNR-C score, which consists of CRP levels, pathological T score, lymph node density, resection margins, age, and tumor size, was validated in a large cohort of patients." (PMID 39165685, 2024). "Since it has been shown that higher CRP levels are reflective of an immune-suppressive tumor microenvironment in RCC, normal and normalized CRP levels in CPI-treated patients might be associated with an improved T cell response." (PMID 37695463, 2024). "Patients with the dMMR tumor had a lower lymphocyte/CRP ratio in our study." (PMID 38975417, 2024). "Additionally, we performed an exploratory analysis of the association between the occurrence of irAEs and factors reported to be predictors of ICI effectiveness, including PD-L1 expression, tumor volume, CRP level, and the NLR." (PMID 39392339, 2024). "In our study, administration of DR30318 resulted in a sustained elevation of CRP levels, potentially indicating an on-target off-tumor toxicity in the stomach, as evidenced by observed gastric-related adverse effects such as anorexia, nausea and mucosal damage (data not shown)." (PMID 38554200, 2024). "Inflammatory cytokines in the tumor microenvironment can stimulate CRP production, which, in turn, may impact tumor cell proliferation, angiogenesis, and metastasis." (PMID 38474160, 2024). "CRP may engage with immunosuppressive cells, such as CD68+ tumor‐associated macrophages and CD15+ tumor‐associated neutrophils (TANs), contributing to a suppressed tumor immune microenvironment." (PMID 38923354, 2024). "CRP‐treated HMDMs inhibited the proliferation of activated T cells, suggesting that CRP may contribute to immunosuppression in tumor tissues by inducing the expression of PD‐L1 in macrophages." (PMID 39564003, 2024). "PF and CRP/Alb have been correlated with clinical outcomes in many types of tumours." (PMID 38496751, 2024). "Chronic inflammation from high CRP levels supports tumour growth, angiogenesis, and metastasis." (PMID 39498386, 2024). "Previous studies in other tumor entities have shown that the dynamics of CRP at the start of CPI therapy could have a prognostic value for the outcome of patients." (PMID 39001486, 2024).
tumor (continued). "Parameters were: sex, age, smoking and alcohol habits, C-reactive protein (CRP) level in the serum, laryngeal subsite involved, differentiation-based histopathologic grading of tumor, neck node involvement, tumor stage, expression levels of PD-L1 (as Combined Positive Score – CPS)." (PMID 39069571, 2024). "Moreover, a previous study suggested that high CRP levels were correlated with OC stage and tumor size." (PMID 38172843, 2024). "Moreover, CRP is part of the host immune response to tumor cells, reflecting the inflammatory state of the body." (PMID 39687883, 2024). "This elevation in CRP is thought to reflect the systemic inflammatory response to the tumor." (PMID 38474160, 2024). "These microbiomes can induce macrophage migration into tumor tissues and activate the inhibited immune microenvironment through elevated IL-6, C-reactive protein (CRP), and vascular endothelial growth factor (VEGF) in systemic inflammation or elevated metabolites such as L-arginine in the TME." (PMID 39497925, 2024). "The term “tumor CRP” is commonly used but until now unexplained." (PMID 39001318, 2024). "Tumor-related proinflammatory cytokine secretion is one of the main mechanisms underlying CACS, in particular interleukin-1 (IL-1), interleukin-6 (IL-6), tumor necrosis factor alpha (TNF-α), and C-reactive protein (CRP)." (PMID 38822976, 2024). "This increase in CRP has been attributed to factors such as tumor necrosis and tumor inflammation." (PMID 38555313, 2024). "Furthermore, C-reactive protein is produced by hepatocytes in response to cytokines, especially IL-6, released by leukocytes within the tumor microenvironment." (PMID 38673838, 2024). "Significantly more of these patients had a high-grade tumour compared to those with low CRP levels." (PMID 39613865, 2024). "Mechanistically, normal and normalized CRP levels following systemic CPI therapy might be a sign for improved T cell response or diminished inflammation due to decreased tumor mass." (PMID 37695463, 2024). "Notably, the baseline CRP levels in our patient cohort were significantly elevated above this tumor-specific threshold, indicating a hyperinflammatory state." (PMID 39703501, 2024). "Patients with a heightened tumor burden, intensified pretreatment, and elevated baseline levels of C-reactive protein, ferritin, D-dimer, and proinflammatory cytokines may face increased susceptibility to CRS and severe manifestations thereof." (PMID 39204130, 2024). "Beside Vpr, age, HIV viremia, HCV viremia, CRP, and IL-6 were also related with tumor occurrence." (PMID 38166062, 2024). "Based on the close connection between chronic inflammation and tumorigenesis, inflammatory markers, such as CRP, might be helpful to predict and prognosticate tumor response to CPI-based therapy." (PMID 37695463, 2024). "This study suggested that CRP levels reflect the patient’s systemic reaction to the tumor." (PMID 39857647, 2024). "Tumor growth induces tissue inflammation, including IL‐6, which elevates CRP levels." (PMID 38923354, 2024). "However, a subsequent decrease in CRP levels is considered to represent tumour shrinkage because CRP levels have been reported to be proportional to tumour size." (PMID 39516365, 2023). "Moreover, we found that total serum cholesterol inversely correlated with the tumor diameter as well as with serum CRP and overall survival." (PMID 37024569, 2023). "High CRP level is a marker of an ongoing inflammatory process that favours tumour development." (PMID 37990536, 2023). "Immunohistochemical staining for protein expression, such as PD‐L1, is notoriously challenging due to the tissue heterogeneity, thus, analyzing CRP could even out the limitations of tumor‐based analyzes." (PMID 37329173, 2023). "The discrepancy may also reflect the differences in CRP assays across the globe or a difference in baseline CRP levels as CRP levels appear to differ across patients, neoadjuvant therapies and tumor histologies." (PMID 37662605, 2023).
tumor (continued). "Among the markers of inflammation, only fibrinogen could predict the tumor grading on each grading state, whereas CRP and ESR differentiate only G1 from the other two grades of G2 and G3, without significant differences between the last two grades." (PMID 38137862, 2023). "CRP can also be an indicator of an immune response against tumour antigens." (PMID 37083267, 2023). "The relation between tumor dynamics and CRP concentrations was best characterized by a linear model relating the ratio of TS at any given time to baseline TS (i.e., x-fold change in TS from baseline TS, (Tumor size (t)Baseline tumor size), to CRP production rate constant (Kin)." (PMID 38001689, 2023). "These CRP-related inflammatory evidence may be the potential role of the tissue injuries which related to the tumor consequence of inflammatory response." (PMID 37009523, 2023). "We also compared the plasma levels of cytokines and acute inflammatory markers, namely, the erythrocyte sedimentation rate (ESR), c-reactive protein (CRP), and fibrinogen, along with the tumor markers, carcinoembryonic antigen (CEA) and carbohydrate antigen 19.9 (CA 19.9), in CRC patients." (PMID 38137862, 2023). "During the training phase of the model, univariate analysis indicated that the CRP to albumin ratio, postoperative CRP, lymphocytes, surgical duration, postoperative albumin, pre-operative red blood cells, tumor size, TNM, and ASA score were major predictive factors for anastomotic leakage." (PMID 35953684, 2023). "It remains unclear if this increase of tumor myeloid cells and serum CRP was due to radiation-induced inflammation or due to a susceptibility of localized infection." (PMID 36251031, 2023). "Overall, CRP-spike may reflect the early post-treatment activation of anti-tumour immunity and subsequent tumour shrinkage." (PMID 39516365, 2023). "Serum CRP levels, which are identified by the activation of proinflammatory cytokines, might lead to tumour invasion, progression, and the formation of metastases." (PMID 38132403, 2023). "Recent studies reported different biomarkers associated with the occurrence of CRS and/or ICANS, such as lactate dehydrogenase (LDH), as marker for tumor burden, the inflammatory markers C-reactive protein (CRP) and ferritin, and platelet count as an indicator for hematopoietic reserve." (PMID 38001703, 2023). "The CRP level in the normal group was 3.1 mg/dl and in the tumour group was 4.8 mg/dl (p < 0.001)." (PMID 37083267, 2023). "Our main hypothesis was that incorporation of CRP levels to prognostication would improve the predictive value of using sole tumor PD‐L1 TPS." (PMID 37329173, 2023). "CRP is an acute reactive protein mainly produced in hepatocytes, which is regulated by proinflammatory cytokines such as interleukin 6, which contributes to the tumor microenvironment, and supports tumor angiogenesis, proliferation, growth, and metastasis." (PMID 36890182, 2023). "By contrast, we found that high-density lipoprotein (HDL) cholesterol inversely correlated with the BMI, C-reactive protein (CRP) and overall survival and total cholesterol inversely correlated with the tumor diameter, serum CRP and overall survival in these LUAD patients." (PMID 37024569, 2023). "Inflammatory cytokines IL-1 and IL-6, secreted by tumor and stromal cells, could induce the rise of CRP." (PMID 38053048, 2023). "The existence of muscle mass reduction because of SMMI is related not only to malnourishment but could also be the consequence of tumor cachexia; this phenomenon is supported by higher levels of C-reactive protein in men and women with low phase angle." (PMID 37371791, 2023). "Finally, systemic inflammation, characterized by the presence of CRP, leads to further physiological disorders, autoimmune-supposed conditions, and neoplasms." (PMID 37873776, 2023).